LIMK1 (LIM domain kinase 1)
Diseases named in the same sentence as LIMK1 in open-access papers (continued):
Sharing a sentence is not in itself a finding about the gene and the disease.
benign prostatic hyperplasia (4 papers, 2007 to 2021). A non-cancerous nodular enlargement of the prostate gland. "The results demonstrated that the positive expression rate of LIMK1 in PCa tissues was significantly higher than that of benign prostatic hyperplasia tissues (77.1% vs 26.0%, respectively; P < .001)." (PMID 32168432, 2020). "A total of 215 cases of LIMK1‐positive expression were seen in 279 cases of PCa tissues, while a total 13 cases of LIMK1‐positive expression were observed in 50 cases of benign prostatic hyperplasia tissues." (PMID 32168432, 2020). "LIMK1 may have a role in urethral obstruction and bladder outlet obstruction in men with benign prostatic hyperplasia." (PMID 35011645, 2021). "To understand the functional role of LIMK1 on cellular morphology, we investigated the effects of ectopic expression of LIMK1 in benign prostatic hyperplasia (BPH-1) cells." (PMID 17559677, 2007). "LIMK1 may have a role in urethral obstruction and bladder outlet obstruction in men with benign prostatic hyperplasia (BPH)." (PMID 35011645, 2021). "A total of 279 PCa specimens from patients who underwent radical prostatectomy and 50 benign prostatic hyperplasia (BPH) specimens were collected to construct tissue microarray, which were subjected to immunohistochemical staining for LIMK1 expression subsequently." (PMID 32168432, 2020). "Ectopic expression of LIMK1 in benign prostatic hyperplasia cells (BPH), which naturally express low levels of LIMK1, resulted in appearance of abnormal mitotic spindles, multiple centrosomes and smaller chromosomal masses." (PMID 17559677, 2007).
cervical cancer (4 papers, 2022 to 2024). A primary or metastatic malignant neoplasm involving the cervix. "Through the detection of cervical cancer cell functions, it was found that the activation of ROS and p-Src induced by LIMK1 is an early event that promotes the migration, proliferation, and invasion of cervical cancer cells." (PMID 38975937, 2024). "The effects of regulating ROS and p-Src expression on LIMK1 in the migration/invasion and proliferation of cervical cancer cells were evaluated through cellular functional assays." (PMID 38975937, 2024). "In summary, LIMK1 promotes F-actin expression and cervical cancer development by regulating the oxidative stress/src-mediated p-FAK/p-ROCK1/2/p-Cofilin-1 pathway." (PMID 38975937, 2024). "Our results suggest that LIMK1 can contribute to the development of cervical cancer by regulating the Src-mediated signaling pathway." (PMID 38975937, 2024). "Comparison of scratch spacing between the Saracatinib-NC group and Saracatinib-LIMK1 overexpression group of cervical cancer cells reveals that Saracatinib reverses the effect of LIMK1 on the migration of cervical cancer cells." (PMID 38975937, 2024). "Our results suggest that LIMK1 can promote the invasion and metastasis of cervical cancer cells by regulating the expression of actin." (PMID 38975937, 2024). "The role of LIMK1 in the invasion, metastasis, and proliferation of cervical cancer was evaluated by cell scratch, Transwell, and monoclonal experiments." (PMID 38975937, 2024). "At the same time, the efficacy of LIMK1 as a therapeutic target can also be verified in clinical trials, providing a new option for the treatment of cervical cancer." (PMID 38975937, 2024). "In this study, we firstly investigated in cancer and paracancerous tissues of cervical cancer patients, and we found that LIMK1 expression was significantly higher in cervical cancer tissues than in paracancerous tissues." (PMID 38975937, 2024). "Studies have shown that the expression level of LIMK1 in cervical cancer tissues is significantly higher than that in normal tissues, and it is closely related to the stage, grade, and prognosis of cervical cancer." (PMID 38975937, 2024). "Our study reveals the mechanism of LIMK1 in the progression of cervical cancer and provides new ideas for the treatment of cervical cancer." (PMID 38975937, 2024). "In conclusion, our study reveals the mechanism of action of LIMK1 in cervical cancer progression, suggesting that LIMK1 can promote the development of cervical cancer by regulating the oxidative stress/Src-mediated p-FAK/p-ROCK1/2/p-Cofilin-1 pathway." (PMID 38975937, 2024). "In the future, the effect of LIMK1 in the treatment of cervical cancer can be verified through genetic analysis and drug therapy trials." (PMID 38975937, 2024). "In conclusion, our study reveals the mechanism of LIMK1 in the progression of cervical cancer and provides new targets and ideas for the treatment of cervical cancer." (PMID 38975937, 2024). "First, we used immunohistochemical staining to detect the expression of LIMK1 in cancer and pericancerous tissues of human cervical cancer." (PMID 38975937, 2024). "Cell scratch, Transwell, and monoclonal experiments suggested that LIMK1 promoted the invasion, metastasis, and proliferation of cervical cancer cells." (PMID 38975937, 2024). "The results suggest that LIMK1 promotes the invasion, metastasis, and proliferation of cervical cancer cells and promotes cervical cancer development by regulating the oxidative stress/SRC-mediated p-FAK/p-ROCK1/2/p-Cofilin-1 pathway." (PMID 38975937, 2024). "In our study, we found that LIMK1 can promote the expression of actin in cervical cancer cells." (PMID 38975937, 2024). "The role of LIMK1 in the growth of cervical cancer was evaluated by HE staining." (PMID 38975937, 2024). "In this study, we explored the mechanism of action of LIMK1 in cervical cancer progression." (PMID 38975937, 2024).
cervical cancer (continued). "In addition, LIMK1 can also contribute to the development of cervical cancer by regulating the Src-mediated signaling pathway." (PMID 38975937, 2024). "Similarly, comparison between the NAC-NC group and NAC-LIMK1 overexpression group of cervical cancer cells shows that NAC reverses the effect of LIMK1 on cervical cancer cells." (PMID 38975937, 2024). "It indicated that LIMK1 plays an important role in the progression of cervical cancer." (PMID 38975937, 2024). "In addition, we also found that LIMK1 can contribute to the development of cervical cancer by regulating oxidative stress and SRC-mediated signaling pathways." (PMID 38975937, 2024). "At present, there have been some studies on the role of LIMK1 in cervical cancer." (PMID 38975937, 2024). "Future studies could further explore the interaction of LIMK1 with other signaling pathways and molecular mechanisms, as well as develop therapies targeting LIMK1, to provide better solutions for the treatment of cervical cancer." (PMID 38975937, 2024). "The enhancement of LIMK1 expression promoted cervical cancer progression." (PMID 36341390, 2022). "Therefore, we speculate that LIMK1 plays an important role in the occurrence and development of cervical cancer by regulating the oxidative stress/Src-mediated signaling pathway." (PMID 38975937, 2024). "Therefore, we speculate that LIMK1 plays an important role in the occurrence and development of cervical cancer." (PMID 38975937, 2024).
melanoma (4 papers, 2014 to 2022). A malignant, usually aggressive tumor composed of atypical, neoplastic melanocytes. "Targeting LIMK1 with small molecular inhibitors has been shown to reduce migration and invasion of malignant melanoma, suggesting increased activity would promote malignancy." (PMID 35560144, 2022).
mental disorder (4 papers, 2019 to 2025). A disease that has its basis in the disruption of mental process. "Because LIMK1 is genetically linked to a number of neurological and mental disorders, the present study suggests that LIMK1-dependent abnormalities in brain development may contribute to these disorders." (PMID 31319858, 2019).
metastatic disease (4 papers, 2014 to 2025). "Limk1 is a key regulator of the actin cytoskeleton, cell motility, and invasion, and is thought to be a therapeutic target for metastatic disease." (PMID 25003638, 2014).
non-small cell lung carcinoma (4 papers, 2019 to 2021). A group of at least three distinct histological types of lung cancer, including non-small cell squamous cell carcinoma, adenocarcinoma, and large cell carcinoma. "The overexpression of miR-125a-5p or knockdown of LIMK1 was found to lead to decreased viability of non-small cell lung cancer tissues and cells, decreased IC50 of cisplatin and downregulated the expression of drug-resistant proteins." (PMID 32427576, 2020). "Likewise, a recent research discovered that miR-143 could affect LIMK1 expression in non-small cell lung cancer (NSCLC) tissues inversely." (PMID 31541994, 2019).
prostate tumor (4 papers, 2007 to 2014). "In this study, we investigated the effects of ectopic expression of LIMK1 on cellular morphology, cell cycle progression and expression profile of LIMK1 in prostate tumors." (PMID 17559677, 2007). "We also show that expression of LIMK1 is higher in prostate tumors with higher Gleason Scores and incidence of metastasis." (PMID 17559677, 2007). "Increased expression of LIMK1 in luminal cells has been reported also in advanced prostate tumors." (PMID 21219645, 2011). "We also noted increased expression of both MT1-MMP and LIMK1 in prostate tumor tissues." (PMID 21219645, 2011). "However, the precise role of LIMK1 in development of abnormal cellular processes, which might facilitate prostate tumor growth and behavior, is unclear." (PMID 17559677, 2007). "To understand the clinical relevance of LIMK1 and MT1-MMP overexpression, we examined the expression profiles of LIMK1 and MT1-MMP in clinical specimens using immunohistochemistry of formalin-fixed paraffin embedded prostate tumors tissues." (PMID 21219645, 2011). "Our studies on expression of LIMK1 in prostate tumors showed that all tumor samples were positive for weak to strong cytoplasmic expression of LIMK1 compared to no or very weak expression in the luminal cells of uninvolved prostate glands." (PMID 17559677, 2007).
breast tumor (3 papers, 2016 to 2023). "All together, these data indicate that LIMK1 and LIMK2 are required for matrix proteolysis by breast tumor cells through control of MT1-MMP function." (PMID 27116935, 2016). "Our results suggest non-redundant roles for LIMK1 and LIMK2 in matrix degradation and invadopodial recruitment of Tks5 in breast tumor cells." (PMID 27116935, 2016).
ischemic stroke (3 papers, 2017 to 2023). A stroke disorder caused by obstruction of blood flow to the brain, due to thrombotic (local blood clot formation) or embolic (due to a blood clot or other material traveling from another site) event. "In mice models of ischemic stroke, LIMK1 overexpression has potential to reduce the number of rods after energy depletion." (PMID 36212686, 2022). "Furthermore, the mechanism of LIMK1 increase induced by EA treatment may be associated with miR-134, which is localized in hippocampal CA1, by negatively regulating LIMK1 to enhance synaptic-dendritic plasticity in the recovery stage of ischemic stroke." (PMID 28116173, 2017). "Therefore, miR-134-mediated LIMK1 was involved in EA-induced hippocampal synaptic plasticity, which served as a contributor to improving learning and memory during the recovery stage of ischemic stroke." (PMID 28116173, 2017).
liver cancer (3 papers, 2021 to 2025). An epithelial or non-epithelial malignant neoplasm that arises from the liver. "This was in alignment with previous bioinformatic studies which have shown the correlation of cytoskeletal markers, such as LIMK1, to a higher hazard ratio of death in liver cancer patients." (PMID 35241781, 2022). "However, further research reveals that in hepatic cancer cells, upregulated H19 functions as a ceRNA by sponging miR-520a-3p, thereby relieving its suppressive effect on LIM domain kinase 1 (LIMK1), an enzyme that promotes HCC cell proliferation, metastasis, and inhibits apoptosis." (PMID 40781643, 2025). "Comparing normal liver tissue samples (225 patients) and liver hepatocellular carcinoma (LIHC) samples (371 patients), the expression of the genes: RhoA, Rac1, LIMK1, LIMK2, ROCK1, ROCK2, MLCK2, and PAK4 is upregulated in liver cancer." (PMID 35241781, 2022). "To identify pharmacological means to alter 2D cell migration in liver cancer, we targeted key regulators of the Rho GTPases, including calcium signaling, Rac1, PAK4, LIMK1, MLCK, and actomyosin contractility." (PMID 35241781, 2022). "With the aim of evaluating the prognostic effects of LIMK1 and LIMK2, we performed a Kaplan-Meier survival analysis on liver cancer (HCC) RNA-seq data, collected from 364 patients." (PMID 34843456, 2021).
viral infection (3 papers, 2013 to 2023). "As all these studies have highlighted the direct involvement of LIMK1, via its activation, in the viral infection process, inhibitors of LIMK1 have been developed as a new approach to block viral infection." (PMID 36899941, 2023). "In particular, HIV binding to CXCR4 activates actin regulators such as LIMK1 and cofilin, promoting actin dynamics necessary for viral infection of resting T cells." (PMID 23782904, 2013).
Anaplastic Thyroid Cancer (2 papers, 2014 to 2017). "In anaplastic thyroid cancer, miR-20a could inhibit cellular proliferation and cell invasion via decreasing LIMK1 protein expression." (PMID 28938591, 2017).
cardiac hypertrophy (2 papers, 2019 to 2022). "CircRNA Zinc finger 644 (Circ-Zfp644) enhanced the expression of pro-fibrotic mediator LIM kinase-1 (LIMK1) through sponging miR-93-5p in in vitro model of cardiac hypertrophy." (PMID 35611768, 2022). "Likewise, miR-93 was verified to be downregulated in AngII-treated cardiomyocytes of cardiac hypertrophy, while the function of the inhibition of LIMK1 in CFH needs to be confirmed in future research." (PMID 31541994, 2019).
cognitive delay (2 papers, 2014 to 2025). "We report two individuals harboring LIMK1 de novo variants with dissimilar phenotypes: one exhibited epileptic encephalopathy and developmental delay, while the other showed common variable immune deficiency and glucose dysregulation." (PMID 40491492, 2025). "LIMK1, GTF2I and GTF2IRD1 genes have been related to aspects of cognitive delay." (PMID 25016475, 2014).
cutaneous squamous cell carcinoma (2 papers, 2017 to 2019). "For example, miR-20a inhibits cutaneous squamous cell carcinoma metastasis and proliferation by directly targeting LIMK1." (PMID 30873211, 2019). "Furthermore, in cutaneous squamous cell carcinoma, researchers also found that miR-20a could inhibit A431 and SCL-1 proliferation and metastasis, and LIMK1 was a direct target gene of miR-20a." (PMID 28938591, 2017).
gastric tumor (2 papers, 2016 to 2021). "In this study, we demonstrate that increased LIMK1 expression is associated with gastric tumor differentiation, tumor size, clinical stage, lymph node metastasis, and poor prognosis." (PMID 26871290, 2016). "In addition, we observed that LIMK1 expression was upregulated in paraneoplastic mucosa and gastric tumors with different differentiation degrees, suggesting that high LIMK1 expression levels may contribute to carcinogenesis, clinical progression and differentiation in gastric tumors." (PMID 26871290, 2016). "Therefore, downregulation of LIMK1 may explain, in part, the mechanisms by which DADS inhibits EMT, invasion and proliferation in gastric tumor cells." (PMID 26871290, 2016).
HIV-1 infection (2 papers, 2017 to 2022). The type species of lentivirus and the etiologic agent of acquired immunodeficiency syndrome (AIDS). "Our results contrast with these findings as LIMKi3 inhibited E2-mediated anti-HIV-1 activity and point to potentially different effects of stimuli (HIV-1 vs. E2) as well as LIMKs (LIMK1 vs. LIMK 1 and 2) on HIV-1 infection." (PMID 35418661, 2022). "Although inhibiting LIMK1 expression blocks HIV-1 infection, no highly specific LIMK inhibitor is available." (PMID 28381571, 2017).
memory impairment (2 papers, 2020 to 2021). "Nevertheless, our results suggest that intervention of LIMK1/cofilin may provide a potential strategy to improve synaptic function and memory impairment associated with AD patients." (PMID 34315506, 2021).
preeclampsia (2 papers, 2013 to 2020). Preeclampsia is a hypertensive disorder of pregnancy that is characterized by new-onset hypertension with proteinuria presenting after 20 weeks of gestation, and depending on mild or severe forms may initially present with severe headache, visual disturbances, and hyperreflexia. "LIMK1 downregulation is associated with preeclampsia; its upregulation in TGCs, therefore, could regulate extensive cytoskeletal rearrangements upon differentiation and thereby may have a role in implantation." (PMID 32762732, 2020). "While aberrant oxygenation and HIF activity have previously been associated with preeclampsia, its ability to regulate LIMK1 has particular relevance, given that LIMK1 has recently been shown to be important for tumor cell invasion in humans as well as collective cell migration in D. melanogaster." (PMID 23437279, 2013).
prostate adenocarcinoma (2 papers, 2007 to 2011). "A variable cytoplasmic staining of LIMK1 from very weak (Figure 5B1) to strong (Figure 5B4) was noted in poorly differentiated prostate adenocarcinomas." (PMID 17559677, 2007). "All of the positive staining (weak to strong positive) of LIMK1 were located in cytoplasm or cytoplasm/nucleus in tumor cells of prostate adenocarcinoma, while only weak staining (0-1+) in the cytoplasm of the glandular epithelium was noted in normal prostate tissues." (PMID 21219645, 2011). "Although increased expression of MT1-MMP in prostate adenocarcinoma has already been reported our study showed overexpression of both LIMK1 and MT1-MMP in the same tumor samples, which supports our in vitro studies and shows an association between LIMK1 and MT1-MMP expressions in clinical samples." (PMID 21219645, 2011). "In addition, most of tumor cells of prostate adenocarcinoma had higher cytoplasmic and nuclear expression of LIMK1 and MT1-MMP, compared to normal prostate tissues." (PMID 21219645, 2011).
Stroke (2 papers, 2021 to 2025). Sudden impairment of blood flow to a part of the brain due to occlusion or rupture of an artery to the brain. "These insights will serve as a rational guide for future scaffold optimization and feature prioritization in the design of LIMK1-targeted therapeutics for stroke." (PMID 41011194, 2025). "Although LIMK1 is upstream of cofilin in the signaling cascade, direct cofilin modulation offers a novel strategy for therapeutic intervention in stroke." (PMID 41011194, 2025). "This study presents a comprehensive computational framework to identify and repurpose LIMK1 inhibitors for direct targeting of cofilin in stroke therapy." (PMID 41011194, 2025).
supravalvular aortic stenosis (2 papers, 2014 to 2021). SupraValvar Aortic Stenosis (SVAS) is characterized by the narrowing of the aorta lumen (close to its origin) or other arteries (branch pulmonary arteries, coronary arteries). "The most enriched ARCHS4 kinase pathway, LIMK1, associates with both nervous system (stimulate axon outgrowth) and cardiac- (predisposing to Supravalvular Aortic Stenosis) related pathways (GeneCards)." (PMID 34445674, 2021). "One study that examined two families with a partial WS phenotype, including supravalvular aortic stenosis (SVAS) and deficits in visuospatial construction, found that affected family members were hemizygous for the elastin (ELN) and LIM-Kinase1 (LIMK1) genes, which lie within the WSCR." (PMID 25057328, 2014).